USP7 (ubiquitin specific peptidase 7)
Diseases named in the same sentence as USP7 in open-access papers (continued):
Sharing a sentence is not in itself a finding about the gene and the disease.
colitis (3 papers, 2022 to 2025). Inflammation of the colon. "In an adoptive-transfer-induced colitis model, Treg cell USP7 loss abrogates the capacity to resolve inflammation, suggesting the role of USP7 in adaptive immunity." (PMID 35145062, 2022). "Collectively, these results suggest that USP7 inhibition is a potential therapeutic strategy for attenuating intestinal oxidative stress and ameliorating colitis." (PMID 39887666, 2025). "Notably, the USP7 inhibitor, P5091, inhibits oxidative stress and colitis in vivo." (PMID 39887666, 2025). "We speculate that the colitis and enteritis observed in the ApcminUsp7 cKO intestine may promote inflammation-associated CRC development over time, which may compensate for the tumor-suppressive effect of Usp7 loss in these animals." (PMID 36669491, 2023). "Collectively, these results demonstrate that the USP7 inhibitor P5091 inhibits oxidative stress and attenuates DSS‐induced colitis in vivo." (PMID 39887666, 2025). "Although NRF2 overactivation can also exacerbate colitis, we found that the USP7 inhibitor P5091 relieved oxidative stress and attenuated gut inflammation in a DSS‐induced colitis mouse model, suggesting the clinical translation of USP7 inhibitors for IBD treatment." (PMID 39887666, 2025). "Genetic deletion, but not pharmacological inhibition, of Usp7 in Apc+/− intestine induces colitis and enteritis." (PMID 36669491, 2023). "Interestingly, our data showed that pharmacological inhibition of USP7 in vivo in Apcmin mice was well tolerated and resulted in a significant decrease in tumor numbers with no signs of colitis or enteritis after 21 days treatment." (PMID 36669491, 2023). "Intriguingly, no colitis or enteritis was observed in any of the collected mice, suggesting that pharmacological inhibition of USP7 could be a safe option for patients with germline APC mutation." (PMID 36669491, 2023).
diabetic foot ulcer (3 papers, 2022 to 2024). "Inhibition of USP7 also mitigates AGE-induced cell cycle arrest and senescence in HUVECs, positioning USP7 as a promising therapeutic target for diabetic foot ulcer treatment." (PMID 38377027, 2024). "To explore the biological function of USP7 in diabetic foot ulcer, we transduced corresponding shRNAs targeting USP7 in HUVECs treated with AGEs." (PMID 35538032, 2022). "Our results showed that USP7 expression is increased in diabetic foot ulcer and in human umbilical vein endothelial cells (HUVECs) after treatment with AGEs." (PMID 35538032, 2022). "Herein, we found that USP7 is highly expressed in patients with diabetic foot ulcer and in HUVECs after AGEs treatment." (PMID 35538032, 2022). "USP7 expression was significantly elevated in diabetic foot ulcer tissues and further increased in lesions with high DUSS." (PMID 35538032, 2022). "Herein, we aimed to explore the role of USP7 in diabetic foot ulcers and provide novel strategies for the treatment of diabetic foot ulcers." (PMID 35538032, 2022). "USP7 is a potential target for the treatment of diabetic foot ulcers." (PMID 35538032, 2022). "USP7 was found to be highly expressed in diabetic foot ulcers with high DUSS." (PMID 35538032, 2022). "USP7 may be a promising target for the treatment of diabetic foot ulcers." (PMID 35538032, 2022).
esophageal cancer (3 papers, 2017 to 2024). A primary or metastatic malignant neoplasm involving the esophagus. "However, metformin can inhibit esophageal cancer proliferation through the upregulation of USP7, suggesting that USP7 has different effects on tumorigenesis in the different cancer types." (PMID 31133011, 2019).
esophageal squamous cell carcinoma (3 papers, 2021 to 2024). Esophageal squamous cell carcinoma (ESCC) is a type of esophageal carcinoma (EC) that can affect any part of the esophagus, but is usually located in the upper or middle third. "Inhibition of USP7 reduced cell growth of esophageal squamous cell carcinoma and activated ERS to induce NOXA-mediated apoptosis." (PMID 35432716, 2022).
gastric tumor (3 papers, 2020 to 2025). "USP7 is overexpressed in some cancer types, e.g., gastric tumor cells, and its levels often correlate with the expression of PD-L1 immune checkpoint inhibitor, which suggests that USP7 might facilitate the stabilization of PD-L1." (PMID 36428632, 2022).
large cell carcinoma (3 papers, 2015 to 2025). A malignant epithelial neoplasm composed of large, atypical cells. "Then, we further investigated the USP7 protein expression in 110 primary squamous cell carcinoma and large cell carcinoma and their adjacent normal lung tissues by IHC using tissue microarrays (TMA)." (PMID 25519684, 2015). "USP7 overexpression may regulate the survival and invasive properties of squamous cell carcinoma and large cell carcinoma cells, and may serve as a molecular target." (PMID 25519684, 2015). "Furthermore, Kaplan-Meier analysis revealed that the patients with high USP7 levels had significantly shorter overall survival than those with low USP7 expression in 110 squamous cell carcinoma and large cell carcinoma patients." (PMID 25519684, 2015). "To investigate whether USP7 overexpression correlates with clinical squamous cell carcinoma and large cell carcinoma progression, we analyzed USP7 expression in the cohort of 110 squamous cell carcinoma and large cell carcinoma patients." (PMID 25519684, 2015). "Thus, we showed that high USP7 levels promote squamous cell carcinoma and large cell carcinoma progression." (PMID 25519684, 2015).
latent infection (3 papers, 2009 to 2020). "We now present evidence that the USP7 interaction is not limited to soluble EBNA1 but also occurs with EBNA1 bound to EBV episomes where it could regulate the plasmid maintenance and transcriptional functions of EBNA1 in EBV latent infection." (PMID 19834552, 2009).
lung neuroendocrine tumors (3 papers, 2017 to 2025). "In contrast, USP‐7 low expression has been identified in some neuroendocrine lung tumors and in nonsmall cell lung adenocarcinoma, suggesting that the role of USP‐7 can vary across different cancer types and may differently influence tumor behavior." (PMID 40555607, 2025). "The identification of CCDC6 as a novel USP7 substrate has provided the rationale to establish that the USP7 inhibitor, P5091, by downregulating CCDC6 protein, can modulate the PARP-inhibitors sensitivity in lung neuroendocrine tumors." (PMID 28415632, 2017). "Moreover, we have reported a combined effect of the inhibitors of USP7 and PARP enzymes in the treatment of lung neuroendocrine tumor cells expressing USP7 and CCDC6 proteins." (PMID 28415632, 2017).
myocardial infarction (3 papers, 2021 to 2025). Gross necrosis of the myocardium, as a result of interruption of the blood supply to the area, as in coronary thrombosis. "USP7 protein expression was upregulated in male mice 1 h and 6 h after myocardial infarction." (PMID 35710902, 2022).
renal carcinoma (3 papers, 2021 to 2024). A carcinoma arising from the epithelium of the renal parenchyma or the renal pelvis. "USP7 altered cell cycle G1/S phases and regulated renal cancer cell proliferation by targeting ARMC5." (PMID 37259026, 2023). "To evaluate whether USP7 is essential for tumor growth in vivo, we established the human renal cancer xenograft by subcutaneously injecting OS-RC-2 cells with or without USP7 knockdown into nude mice." (PMID 39406703, 2024). "Moreover, USP7 altered cell cycle G1/S phases and regulated renal cancer cell proliferation by targeting ARMC5." (PMID 33544460, 2021).
renal cell carcinoma (3 papers, 2021 to 2024). "For example, USP7 delayed renal cell carcinoma progression via deubiquitylating and stabilizing ARMC5." (PMID 38129408, 2023). "While the detailed mechanisms remain unclear, functional blocking of ERBB receptors by afatinib, which is in phase II clinical trial for renal cell cancers, was shown to induce proteasome-medicated HIF2α degradation by transcriptionally inhibiting USP7." (PMID 39406703, 2024). "A previous study indicated that USP7 might interact with and deubiquitinate tumor suppressor ARMC5 in renal cell carcinoma, and silencing of USP7 promoted 786-O cell proliferation in vitro." (PMID 39406703, 2024).
Schaaf-Yang syndrome (3 papers, 2016 to 2020). "To date, there are no studies on circadian rhythm and sleep disruptions in individuals with Schaaf-Yang syndrome or individuals with USP7 mutations, due to small sample size and recent clinical discovery." (PMID 32315313, 2020). "Moreover, deletion or mutation of USP7 has been shown to result in a neurodevelopmental disorder with overlapping symptoms to Schaaf-Yang syndrome (OMIM #615547), caused by mutations of MAGEL2." (PMID 29441128, 2018). "In addition, five out of seven individuals with USP7 mutation had seizures, indicating a higher prevalence than in PWS (10%–20%) or Schaaf-Yang syndrome (only one described case)." (PMID 28933382, 2016). "The seven individuals with USP7 haploinsufficiency manifested hypotonia, hypogonadism, and developmental delay/intellectual disability, similar to both PWS and Schaaf-Yang syndrome." (PMID 28933382, 2016).
Sepsis (3 papers, 2025). Sepsis is defined as life-threatening organ dysfunction caused by a dysregulated host response to infection. "This study aims to explore the mechanism of ubiquitin-specific peptidase 7 (USP7) in sepsis with the involvement of intercellular adhesion molecule-1 (ICAM-1)." (PMID 41170880, 2025). "Of particular note is the fact that the TGF-β signaling pathway has been shown to promote sepsis-induced ferroptosis of lung epithelial cells in ALI through transcriptional regulation of USP7." (PMID 40246841, 2025). "A sepsis model was established using lipopolysaccharide (LPS) induction in WT and USP7-/- mice, and various assays were conducted to evaluate survival rates, organ damage, inflammatory markers, and protein interactions." (PMID 41170880, 2025). "Targeting USP7 may represent a potential therapeutic approach to mitigate sepsis-related inflammation and organ damage." (PMID 41170880, 2025). "USP7 upregulated SOX9 expression through deubiquitination, and SOX9 suppressed miR-96-5p expression by binding to the miR-96-5p promoter region, thereby promoting NLRP3 expression and then exacerbating sepsis-induced myocardial injury and cardiomyocyte pyroptosis." (PMID 40041174, 2025).
small cell lung carcinoma (3 papers, 2022 to 2025). Small cell lung cancer (SCLC) is a highly aggressive malignant neoplasm, accounting for 10-15% of lung cancer cases, characterized byrapid growth, and early metastasis. "In addition, USP7 inhibition was reported to restore chemosensitivity in MYCN-overexpressing small-cell lung cancer models." (PMID 37762082, 2023). "There was a recent report that USP7 could deubiquitinate KRAS and maintain its expression in small cell lung cancer cells." (PMID 40473213, 2025).
T-cell leukemia (3 papers, 2019 to 2024). A malignant disease of the T-lymphocytes in the bone marrow, thymus, and/or blood. "The fusion gene STIL-TAL1 and mutations in BCL11B, NOTCH1, and USP7 have been associated with T-cell leukemia." (PMID 38363891, 2024). "The fusion gene STIL-TAL1 and mutations in BCL11B, NOTCH1, and USP7 have also been found and all been associated with the occurrence of T-cell leukemia." (PMID 38363891, 2024). "In certain contexts of T cell leukemia and multiple myeloma, ubiquitin-specific protease 7 (USP7) drives the oncogenic programs." (PMID 36490346, 2022). "USP7 cooperates with NOTCH1 to drive the oncogenic transcriptional program in T cell leukemia." (PMID 30898977, 2019). "In this study, we have demonstrated a previously unidentified role for the deubiquitinase complex of USP7 and USP11 in regulating LCK kinase signaling and therapy response in T cell leukemia." (PMID 36490346, 2022).
ZIKV infection (3 papers, 2024 to 2025). "In addition, the study suggests that Wnt/β-catenin pathway may be involved in cell death associated with ZIKV infection, given that USP7-ATRT, cell line with best outcomes, had shown hyperactivity of this specific pathway." (PMID 39347716, 2024). "Previously, we demonstrated a aggressive paediatric atypical teratoid rhabdoid tumour (ATRT) cell line, USP7-ATRT, to have CSC properties and to be highly susceptible to ZIKV infection and oncolysis." (PMID 41166287, 2025). "Integrating the 49-plex ELISA and RNA-Seq data, we observe 27 of the 49-plex proteins to be significantly differently expressed or secreted by USP7 or USP13 following ZIKV infection." (PMID 40240536, 2025). "When compared to sham group, OS of USP7-ATRT tumor-bearing mice treated with ZIKV infection was statistically increased (P = 0.0046) and 60% of the group had complete metastatic remission (n = 3)." (PMID 39347716, 2024). "Reduction of tumor growth ratio in USP7-ATRT and USP13-MED was also observed, even though DAOY cell line had a poor response to ZIKV infection, which fits in vitro findings." (PMID 39347716, 2024).
atherosclerosis (2 papers, 2021 to 2024). A disease characterized by the build-up of fatty material and calcium deposition in the arterial wall resulting in partial or complete occlusion of the arterial lumen. "Our study also provided further insight into the regulatory network and the underlying roles of miR‐15b regulating KDM6B via USP7 in atherosclerosis." (PMID 33434305, 2021). "Combining previous studies with our results, a regulatory network could be proposed in the antagonizing atherosclerosis progression that depletion of miR‐15b promoted USP7 expression to up‐regulate KDM6B." (PMID 33434305, 2021). "Accumulating evidence has also elucidated that up‐regulation of USP7 could enhance the osteogenic differentiation of human adipose‐derived stem cells (hASCs) to inhibit the progression of osteogenesis, suggesting that overexpression of USP7 could relieve atherosclerosis." (PMID 33434305, 2021).
cardiac hypertrophy (2 papers, 2022 to 2025). "Mechanically, the administration of USP7 inhibitor p22077 down-regulates multiple signal pathways, which are involved in cardiac hypertrophy and remodeling." (PMID 36386139, 2022). "In this study, we for the first time demonstrated that the deubiquitinase USP7 has a crucial role in regulating Ang II-induced cardiac hypertrophy and cardiac remodeling." (PMID 36386139, 2022). "Here, our data indicated that USP7 expression was increased during Ang II-induced cardiac hypertrophy and remodeling in mice and humans with heart failure, while the administration of its inhibitor p22077 attenuated cardiac hypertrophy, cardiac fibrosis, inflammation, and oxidase stress." (PMID 36386139, 2022). "In addition, our previous study using microarrays of gene expression has reported that USP7 is upregulated in Ang II-induced hypertrophic heart in mice, especially on day 7, suggesting that USP7 may involve in cardiac hypertrophy." (PMID 36386139, 2022). "In addition, our studies demonstrate that USP7 contributes to the pathogenesis of cardiac hypertrophy and suggest that USP7 could be a new therapeutic target for hypertrophic diseases." (PMID 36386139, 2022). "Taken together, these results indicate that the USP7 inhibitor p22077 may modulate cardiac remodeling by targeting and stabilizing a series of substrate proteins, which play important roles cardiac hypertrophy, fibrosis, inflammation, oxidase stress, and the progression of heart failure." (PMID 36386139, 2022). "Thus, our data indicated that USP7 plays an important role in Ang II-induced cardiac hypertrophy and remodeling and may be a novel target for the treatment of hypertrophic cardiovascular diseases." (PMID 36386139, 2022).
chronic leukemia (2 papers, 2021). A slowly progressing leukemia characterized by a clonal (malignant) proliferation of maturing and mature myeloid cells or mature lymphocytes. "Moreover, in chronic leukemia, it has been shown that BCR-ABL could aberrantly phosphorylate USP7 at Tyr243, contributing to the function of USP7 as a deubiquitinase for PTEN." (PMID 34869041, 2021).
chronic obstructive pulmonary disease (2 papers, 2023 to 2025). A chronic and progressive lung disorder characterized by the loss of elasticity of the bronchial tree and the air sacs, destruction of the air sacs wall, thickening of the bronchial wall, and mucous accumulation in the bronchial tree.
head and neck cancer (2 papers, 2021 to 2025). A primary or metastatic malignant neoplasm affecting the head and neck. "USP7 also plays a crucial role in the progression of various types of head and neck cancers." (PMID 41157055, 2025).
head and neck squamous cell carcinoma (2 papers, 2024 to 2025). A squamous cell carcinoma that arises from any of the following anatomic sites: lip and oral cavity, nasal cavity, paranasal sinuses, pharynx, larynx, and salivary glands. "For instance, USP7 interacted with TAZ and removed the K48‐linked ubiquitin chains of TAZ to accelerate the progression of head‐neck squamous cell carcinoma." (PMID 39107958, 2024). "USP7 and PRMT5-dependent G3BP2 stability drives de novo lipogenesis and tumorigenesis in head and neck squamous cell carcinoma." (PMID 39944823, 2025).
heart failure (2 papers, 2022 to 2024). Inability of the heart to pump blood at an adequate rate to meet tissue metabolic requirements. "The major findings are as follows: 1) The expression of USP7 was upregulated both in heart tissues and serum from patients with heart failure, and in Ang II-induced hypertrophic mice hearts." (PMID 36386139, 2022).
Hepatic steatosis (2 papers, 2020 to 2025). Steatosis is a term used to denote lipid accumulation within hepatocytes. "Reasonably, USP7/ZNF638 was also abundantly detected in HCC patients, especially those with liver steatosis, suggesting the central role of USP7 or ZNF638 in DNL-related carcinogenesis." (PMID 33040080, 2020). "In the mice liver steatosis model induced by fructose, USP7 or ZNF638 abrogation significantly ameliorated disease progression." (PMID 33040080, 2020). "Additionally, USP7 knockdown reduced hepatic steatosis and liver injury in ALD mice in vivo." (PMID 40384855, 2025). "To examine the physiological roles of USP7/ZNF638 axis on DNL in vivo, we established the fructose-induced mouse hepatic steatosis model." (PMID 33040080, 2020). "The data indicates that USP7/ZNF638 axis mediates aberrant DNL, which is relevant to hepatic steatosis in vivo." (PMID 33040080, 2020). "Although higher expression of both proteins was observed in tumor tissues comparing with para-tumor tissues, the expression of USP7 and ZNF638 was further increased in patients with liver steatosis, and in these patients, USP7 favored nuclear localization." (PMID 33040080, 2020). "To fully elucidate clinical relevance of USP7 and ZNF638, we immunostained the HCC specimens with or without liver steatosis." (PMID 33040080, 2020).